ACYP2 (acylphosphatase 2)
Diseases named in the same sentence as ACYP2 in open-access papers (continued):
Sharing a sentence is not in itself a finding about the gene and the disease.
cancer (6 papers, 2016 to 2023). A tumor composed of atypical neoplastic, often pleomorphic cells that invade other tissues. "Genome wide association studies have demonstrated that genetic polymorphisms in ACYP2 are associated with telomere length, which has led to studies of the association between ACYP2 and various cancers." (PMID 28039478, 2017). "We investigated the association between single nucleotide polymorphisms (SNPs) in ACYP2, which has been associated with telomere length in several types of cancer, and the risk of CRC in a Chinese Han population." (PMID 28039478, 2017). "Previous studies have revealed an association between the ACYP2 gene and cancer cell metabolism (i.e. pyruvate metabolism and glycolysis/gluconeogenesis)." (PMID 28039478, 2017). "Presently, some articles also found that polymorphism of ACYP2 gene have related to cancers." (PMID 28415712, 2017). "AcPase pathways may be altered in various cancers, and overexpression of ACYP2 could decrease the risk of BC." (PMID 27894080, 2016). "However, the discussion on the relationship between the ACYP2 gene and cancer is still relatively scarce." (PMID 37234166, 2023).
tumor (3 papers, 2016 to 2020). "Our results showed that ACYP2 depletion led to a significant increase of intracellular Ca2+ concentration in the cytoplasm of tumor cells." (PMID 32517717, 2020). "Our data showed that the tumors induced by SF295 cells stably knocking down ACYP2 showed a much slower growth rate and smaller mean tumor volume than the tumors induced by control cells, while this effect could be clearly reversed by BAPTA-AM or calpeptin treatment." (PMID 32517717, 2020). "Under the fluorescence microscope, ACYP2 depletion in U251 and SF295 cells leaded to a significant increase of Ca2+ fluorescence intensity in the cytoplasm of tumor cells relative to the control." (PMID 32517717, 2020).
cardiovascular disease (2 papers, 2011 to 2025). "Common cardiovascular disease phenotypes that are significantly associated with ACYP2 are height, weight, BMI, high‐density lipoproteins, diastolic blood pressure, and total cholesterol." (PMID 40526038, 2025). "To consider whether ACYP2 is relevant to human cardiovascular disease, we queried the Common Metabolic Diseases Knowledge Portal (Accelerating Medicines Partnership – Cardiovascular Disease Knowledge Portal, 2023)." (PMID 40526038, 2025).
ACYP2 also shares sentences with these, for which no sentence is quoted: colorectal cancer (5 papers); neuroblastoma (2); sudden cardiac arrest (2); Alzheimer disease (1); anorexia nervosa (1); autism spectrum disorder (1); bulimia nervosa (1); Cirrhosis (1); edema (1); embryonal tumors (1); ependymoma (1); hearing disorder (1); hepatocellular carcinoma (1); HIV-1 infection (1); low grade glioma (1); metabolic disease (1); neuropathy (1); pharyngeal cancer (1); schizophrenia (1); type 2 diabetes (1).